ENSG00000202216
Gene: Small nucleolar RNA gene on chromosome 2 (179,934,402 to 179,934,527, reverse strand). Ensembl gene ENSG00000202216.
Gene Ontology:
Biological process: RNA processing
Cellular component: nucleolus
Homologues: Orthologues: mouse Snora43 (80% identical), rat AC111292.6 (67% identical). Paralogues in human: SNORA17B (79% identical).